CDK4 (cyclin dependent kinase 4)
Diseases named in the same sentence as CDK4 in open-access papers (continued):
Sharing a sentence is not in itself a finding about the gene and the disease.
diabetes (21 papers, 2010 to 2025). "Cdk4 knockout mice display significantly reduced body size, impaired fertility, and insulin-deficient diabetes due to abnormal postnatal islet cell development." (PMID 40210435, 2025). "Although no previous clinical trials on CDKi have focused on the role of diabetes, in vivo studies have shown that genetic CDK4 loss as well as treatment with the CDKi Palbociclib lead to the reduction in beta-islet pancreatic cells." (PMID 38730711, 2024). "Taken together, these data suggest that the rescue of diabetes in IRS2-null mice by Cdk4-R24C was due to correction of insulin deficiency rather than insulin responsiveness." (PMID 37712417, 2023). "Replacing both endogenous alleles of Cdk4 with Cdk4-R24C prevented diabetes in IRS2-null male mice by rescuing β cell mass, function, and differentiation and restoring cytoplasmic FOXO1 location and nuclear PDX1 abundance in β cells in vivo." (PMID 37712417, 2023). "G1/S CDK complexes play a crucial role in beta cell proliferation in mouse and human, and loss of either CDK4 or Cyclin D2 leads to a dramatic loss of beta cell mass and proliferation, resulting in diabetes." (PMID 37407581, 2023). "Our result is consistent with a prior observation that overexpression of CDK4-R24C under the insulin promoter rescued diabetes due to leptin receptor deficiency." (PMID 37712417, 2023). "CDK4 deficiency in mice gives rise to a range of endocrine-specific phenotypes including diabetes, infertility, dwarfism, and atrophy of the anterior pituitary." (PMID 37893220, 2023). "Islets are primarily comprised of insulin-secreting ß cells and interestingly mice that are null for CDK4 expression develop insulin-deficient diabetes." (PMID 36051751, 2022). "Cdk4-deficient mice display β-cell hypoplasia and develop diabetes, whereas β-cell hyperplasia is observed in mice expressing an active Cdk4R24C kinase." (PMID 20084282, 2010). "Such reproductive alterations are either a direct effect of gene mutation such as cryptorchidism in Hoxa-10 mutant mice or an indirect consequence of declined biological functions of other body systems induced by mutated genes such as diabetes-related infertility in Cdk4-deficient mice." (PMID 38500604, 2024). "Two independent CDK4 knockout alleles were generated in mice and both display a unique endocrine phenotype, which is characterized by the loss of pancreatic beta cells leading insulin deficiency and diabetes, dwarfism and infertility." (PMID 37893220, 2023). "However, loss of CDK4 has been shown to result in insulin-deficient diabetes due to a severe decrease in β-cell growth." (PMID 29523786, 2018). "In contrast, loss of Cdk4 or skeletal muscle–specific deletion of Cdk4’s target, E2F3, depleted oxidative myofibers, deteriorated mitochondrial function, and reduced exercise capacity, while increasing diabetes susceptibility." (PMID 37395281, 2023). "Compared to the control group, diabetes induced a dramatic decrease in Cdk4 expression (P < 0.01), GQD and metformin significantly increased the Cdk4 level of diabetic rats (P < 0.05)." (PMID 35858880, 2022). "Genetic ablation of Cdk4 activity, cyclin D2, or combined E2f1 and E2f2, results in defective maintenance of adult pancreatic β-cells, eventually resulting in severe diabetes." (PMID 20090907, 2010). "Cdk4−/− mice exhibit β-cell hypoplasia and develop diabetes, whereas Cdk4R24C/R24C mice (Cdk4R/R mice), inheriting the p16Ink4a-insensitive Cdk4R24C kinase, exhibit β-cell hyperplasia." (PMID 20084282, 2010). "These two patients were also taking diabetes medications while on CDK4/6 inhibitors." (PMID 39640578, 2024). "We postulated that if loss of cyclin D2/CDK4 activity in β cells is a primary cause of diabetes in IRS2-null mice, then activating CDK4 in vivo might counteract the diabetogenic phenotype in these mice." (PMID 37712417, 2023). "Homozygous replacement of WT Cdk4 with Cdk4-R24C rescued diabetes in Irs2–/– male mice." (PMID 37712417, 2023).
diabetes (continued). "Diabetes suppressed Cdk4 and Irs1 gene expression that was elevated by GQD and metformin indicated these two genes might be the key targets for α-cell proliferation." (PMID 35858880, 2022). "First, we selected the central core sites in the PPI network of AS, DN, DR and found six characteristic genes of diabetes (TYROBP, LCP2, CCL2, CD44, RPL3, CDK4)." (PMID 36755923, 2023). "Mice expressing a constitutively active Cdk4 that cannot bind its inhibitor p16INK4a, a product of the CDKN2A locus, were protected from obesity and diabetes." (PMID 37395281, 2023). "Drugs closely related to diabetes, such as Fenretinide, Dimethylamine parthenolide, Chelerythrine, etc., have obvious positive correlation with LCP2, TYROBP, RPL3, CDK4, and CD44." (PMID 36755923, 2023). "In summary, we report the discovery that CDK4 promotes insulin signaling and FOXO1 degradation in the pancreatic β cell, derepressing Pdx1 expression and rescuing diabetes in Irs2–/– mice." (PMID 37712417, 2023). "After pooling the screened targets of diabetes and cell proliferation from GQD and metformin, the PPI network showed a linear interaction from CDK4 to IRS1." (PMID 35858880, 2022). "After comparing the diabetes related targets of GQD with cell proliferation targets, 4 potential targets (PPARG, TNF, INSR, CDK4) were selected for GQD." (PMID 35858880, 2022). "Contrastingly, mRNAs levels of cell cycle promoters including cyclin-dependent kinase (CDK) 4, (CDK4), CDK6 and Cyclin D1 showed marked reduction during the course of diabetes." (PMID 30720765, 2019). "This is thought to be due to the CDKN2A and CDKN2B genes in this genomic region inhibiting CDK4 and CDK6, which has been demonstrated to influence β cell proliferation and mass, eventually leading to diabetes." (PMID 25430018, 2014). "Because p16 and cyclin D/Cdk4 complexes are known to regulate proliferation of pancreatic islet cell progenitors and p16 was strongly expressed in islets of CAG-rtTA3 mice, we tested CAG-rtTA3:TetOp-16 mice treated with Dox d20-40 for diabetes." (PMID 25481981, 2015). "Cdk4-R24C rescue of Irs2–/– diabetes was not due to improved insulin sensitivity." (PMID 37712417, 2023). "Thus, whole-body homozygous, but not heterozygous, replacement of Cdk4-WT with Cdk4-R24C provided effective protection against diabetes in male mice lacking IRS2." (PMID 37712417, 2023).
metastatic melanoma (21 papers, 2010 to 2025). A melanoma that has spread from its primary site to another anatomic site. "Aberrant regulation of the CDK4/6-cyclin D1 axis is associated with the development of metastatic melanoma and breast cancer." (PMID 35190631, 2022). "In this study, we evaluated the efficacy of arcyriaflavin A (ArcA), a potent inhibitor of the cyclin D1/CDK4 complex, in suppressing aggressive phenotypes of metastatic melanoma." (PMID 39948552, 2025). "Herein, this study investigated the efficacy of ArcA, a potent inhibitor of the cyclin D1/CDK4 complex, in metastatic melanoma cells." (PMID 39948552, 2025). "A phase 1b/2 dose escalation trial in metastatic melanoma (NCT01543698) combined ribociclib (CDK4/6i) with encorafenib (BRAFi) and binimetinib (MEKi)." (PMID 40282469, 2025). "Inversely, metastatic melanoma cell lines with low miR-200a and high CDK6 expression were more susceptible to CDK4/6 inhibition." (PMID 34439268, 2021). "Our results suggest that CDK4 inhibition represents a promising approach for the treatment of metastatic melanoma." (PMID 26201960, 2015). "Combining CDK4/6 (palbociclib) and a MEK inhibitor (trametinib) overcame this resistance, offering a promising strategy for patients with metastatic melanoma who are refractory to BRAF/MEK therapy." (PMID 40282469, 2025). "Here we focus on three targeted therapies for the treatment of metastatic melanoma, namely BRAF, MEK and CDK4/6 inhibitors." (PMID 34025662, 2021). "In our studies, we investigated the antitumor activity of BRAF, MEK and CDK4/6 inhibitors in combination using both treatment responsive and drug-resistant BRAFV600E-mutant metastatic melanoma PDTXs." (PMID 29541385, 2018). "Whole-exome sequencing in patients with metastatic melanoma treated with anti-PD-1 antibodies revealed CDK4 amplification in patients with no clinical improvement." (PMID 37056769, 2023). "miR-200a negatively regulated CDK6 but not CDK4 expression in metastatic melanoma." (PMID 34439268, 2021).
acral melanoma (20 papers, 2014 to 2025). "According to our findings, recent studies have also identified CDK4 amplification as an independent factor associated with reduced overall survival in primary acral melanoma patients." (PMID 40362334, 2025). "Cyclin D1 (CCND1) and CDK4 copy number gains often appear in acral melanoma, suggesting a pathogenic role." (PMID 40282469, 2025). "Cdk4 gain, Ccnd1 gain and the combination of Cdk4 gain and Ccnd1 gain were associated with the poor prognosis of acral melanoma, respectively." (PMID 31358010, 2019). "Additionally, CCND1 amplification and CDKN2A loss—which are common genetic alterations seen in acral melanoma—can activate the CDK4 pathway, promoting primary resistance to therapy." (PMID 41010951, 2025). "Moreover, our previous study of 514 cases of acral melanoma showed that 87% of patients had at least one copy number variant of the CDK4 signaling pathway genes." (PMID 31358010, 2019). "A phase 2 trial of palbociclib (NCT03454919) in 15 patients with advanced acral melanoma and CDK4 pathway alterations found that 20% achieved some tumor shrinkage at 8 weeks, but only 1 was of sufficient magnitude to be considered a partial response." (PMID 40282469, 2025). "Regarding the cell cycle pathway, CDK4/CCND1 amplifications were more common in NAM and CDKN2A/B loss occurred mostly in acral melanoma." (PMID 36983205, 2023). "Identified CNVs in acral melanoma have implicated several genes, including CCND1, CDK4, hTERT, PAK1, GAB2, EP300, YAP1, and MDM2." (PMID 35997352, 2022). "BRAF and NRAS mutations are common in acral melanocytic nevus, whereas acral melanoma shows lower rates of KIT, NF1, BRAF, and NRAS mutations and remarkable copy number variations in genes such as CCND1, CDK4, hTERT, PAK1, and GAB2." (PMID 35997352, 2022). "Aberrations in MAPK, PI3K/AKT/PTEN, TERT, WNT, and CDK4/CDKN2A signaling pathways are frequent in acral melanoma." (PMID 34149718, 2021). "Deletions of gene CDKN2A appear to lead to resistance to immunotherapy and, in combination with the deregulation of CDK4, worsen prognosis in acral melanoma." (PMID 32825510, 2020). "The co-amplifications of the receptor tyrosine kinases KIT and PDGFRA on chromosome 4, as well as CDK4 on chromosome 12, are of particular interest for acral melanoma." (PMID 32825510, 2020). "The driver mutations in the genes RICTOR, CDK4, PDGFRA, KIT were specific for acral melanoma, while the amplification or deletion of the genes CCND2 and CHEK2 are uniquely found in mucosal melanoma." (PMID 32825510, 2020). "Studies have indicated frequent amplification of genes involved in the CDK4 pathway including CCND1 in acral melanoma, indicating the potential for CDK4/6 inhibitors." (PMID 32393283, 2020). "Our previous study found that both CDK inhibitors and specific CDK4/6 inhibitors effectively inhibited the tumor growth in PDX models of acral melanoma containing CDK4 pathway aberration." (PMID 31358010, 2019). "Conversely, mucosal and acral melanomas frequently harbour mutations and/or amplifications of KIT, often associated with cyclin D1 (CCND1) or cyclin-dependent kinase 4 (CDK4) amplifications, but very rarely contain BRAF mutations." (PMID 31581559, 2019). "Recently, palbociclib, an FDA-approved CDK4/6 inhibitor for treating metastatic breast cancer, has been demonstrated to show antitumor effects by inhibiting tumor growth in acral melanoma and mucosal melanoma with CDK4 amplifications in patient-derived xenograft models." (PMID 37239381, 2023). "However, palbociclib only showed a modest effect (20% patients had tumor shrinkage at 8 weeks) as monotherapy in advanced acral melanoma with CDK4 pathway gene aberrations in a phase II clinical study." (PMID 37239381, 2023). "In addition, genetic alterations in CDK4 pathway components (CDK4, CCND1, and CDKN2A), which are particularly common in Asians, have been associated with innate resistance to PD-1 blockade in patients with acral melanoma." (PMID 34149718, 2021).
acral melanoma (continued). "A large cohort analysis in 2017 found that CDK4 gene amplification was higher in acral melanoma (AM), suggesting that CDK4 may be a therapeutic target for AM." (PMID 31358010, 2019). "Additionally, acral melanomas frequently harbor copy number gains in CCND1 and CDK4 and losses of CDKN2A, and a large preclinical study showed that palbociclib monotherapy was effective in treating acral melanoma patient derived xenograft tumors with various alterations to Cyclin–CDK circuitry." (PMID 40282469, 2025). "In addition, acral melanoma frequently exhibits complex structural alterations, including amplifications and deletions of chromosomes, particularly affecting the cyclin D1 (CCND1), cyclin-dependent kinase 4 (CDK4), and telomerase reverse transcriptase (TERT) genes." (PMID 39202970, 2024).
chordoma (20 papers, 2017 to 2025). Chordomas are rare malignant tumors arising from embryonic remnants of the notochord in axial skeleton. "CDK4/6 inhibition appears as a promising strategy to manage advanced chordomas harboring a loss of CDKN2A/2B." (PMID 36505864, 2022). "Palbociclib, a specific inhibitor of CDK4/6, has recently been tested in in vitro cell line chordoma models harboring the loss of CDKN2A and showed an efficient inhibition of the tumor cell growth." (PMID 36505864, 2022). "For example, palbociclib is an approved CDK4/6 inhibitor for chordomas with CDKN2A gene loss and is currently being evaluated in a clinical trial (NCT03110744)." (PMID 36248987, 2022). "RTK activation along with frequent loss of the cell cycle tumor suppressor CDKN2A in chordomas has motivated preclinical repurposing studies with CDK4/6 inhibitors and a Phase II trial involving palbociclib in CDKN2A-null chordoma patients (NCT03110744)." (PMID 36387127, 2022). "Seeking to explore an additional combination agent, abemaciclib was selected as it is an approved CDK4/6 inhibitor, and chordomas have a near universal loss of CDKN2A and p16 resulting in activation of CDK4/6." (PMID 36059685, 2022). "Additionally, homozygous deletions of CDKN2A and CDKN2B genes, which are common in chordoma, suggest potential susceptibility to CDK4/6 inhibitors." (PMID 39941902, 2025). "We conducted a phase II single-arm, open-labeled trial on palbociclib in adult patients with advanced chordomas with p16 (by immunohistochemistry) or CDKN2A (by genomic analysis) loss along with retained CDK4/6 and RB1 expression (by immunohistochemistry or RNA sequencing)." (PMID 40627883, 2025). "Previous studies suggested that chordoma cells exhibiting a loss of CDKN2A (p16) may trigger universal activation of CDK4/6, implying the potential applicability of CDK4/6 inhibitor in chordoma treatment." (PMID 38369555, 2024). "A comprehensive genomic and transcriptomic analyses identified the IGF1R/FGFR/EGFR and CDK4/6 pathways as treatment strategies for chordoma patients." (PMID 41442054, 2025). "Due to limited available RNA sequencing data, we cannot draw any conclusions regarding the predictive value of CDK4 mRNA expression for this chordoma cohort." (PMID 40627883, 2025). "Loss of PTEN and CDKN2A (encoding p16) is one of the most common molecular changes seen in chordomas; poor prognoses are linked to particular inhibitors of the PI3K/AKT/mTOR pathway and CDK4/6." (PMID 39233954, 2024). "The purpose of this study was to elucidate the therapeutic efficacy of CDK4/6 inhibitor for chordoma." (PMID 38369555, 2024). "In summary, our data provide the first clinical evidence and comprehensive genomic profiling including the potential response, and assumed drug resistance markers during application of the CDK4/6 inhibitor in a chordoma patient." (PMID 38369555, 2024). "The success of CDK4/6 inhibitors in other malignancies has motivated their application to chordomas." (PMID 32733369, 2020). "The inactivation of CDKN2A universally activates the CDK4/6 and Rb pathways, which are highly expressed in the chordoma tissues." (PMID 30775316, 2019). "A cetuximab/CDK4/6 inhibitor combination may therefore act synergistically to halt the growth of chordoma tumor cells and provoke a strong NK- and T-cell based antitumor response." (PMID 36387127, 2022).